CCL2 (C-C motif chemokine ligand 2)
Diseases named in the same sentence as CCL2 in open-access papers (continued):
Sharing a sentence is not in itself a finding about the gene and the disease.
tumor (continued). "By altering the expression of chemokines such as CXCL9 and CCL2, radiotherapy can modulate the TME, increasing the likelihood of an effective immune response against the tumor." (PMID 39578426, 2024). "Both CCL2 (also called MCP1) and CSF1 promote M2 polarization and contribute to tumor initiation and progression." (PMID 38550587, 2024). "A major tumor-promoting role for the coexpression of the chemokines CCL2 and CCL5 in tumor cells has been suggested in breast malignancies." (PMID 38928033, 2024). "Results from our bioinformatic study revealed CCL2/CCR2 as one of the five pathways most upregulated within NK cells and HPV − tumor cells (vs. HPV + tumor cells)." (PMID 38468260, 2024). "After irradiation, tumor cells activate the STING/IFN-β signaling pathway to release chemokines, including CCL2, CCL7, and CCL12, via the CCR2 pathway to recruit M-MDSC." (PMID 39464890, 2024). "On the other hand, tumor cells express suppressive molecules (such as indoleamine 2,3-dioxygenase (IDO), adenosine, and CCL2) to inhibit T-cell activity and recruit Tregs to tumor sites, impairing immunotherapy efficacy." (PMID 38520648, 2024). "Higher levels of CCL2 and CCL4 in the tumor tissue of lung adenocarcinoma patients predicted unfavorable survival rates." (PMID 38928238, 2024). "Viral transfection-mediated knockdown of CCL2 diminished AAE’s effects on NK cell infiltration and tumor growth inhibition." (PMID 39206194, 2024). "As an illustration, 20 Gy RT in a pancreatic cancer cell line increased CCL2 production, attracting monocytes expressing the corresponding CCR2 receptor to the irradiated tumour and facilitating tumour progression and angiogenesis." (PMID 38833685, 2024). "Previous studies have reported that CCL2 binds mainly to its receptor, CCR2, to recruit and activate TAMs, which invade tumor sites and promote tumor progression." (PMID 38741887, 2024). "The presence of CCL2 in TME was correlated with overall reduced survival of cancer patients and high levels of tumor grades." (PMID 38360737, 2024). "In a different study, NK cells were engineered to overexpress CCR2B and CCR4 to induce migration toward CCL2- and CCL22-expressing tumor cells, respectively." (PMID 39114657, 2024). "Bidirectional crosstalk between tumor cells and CAFs enhances the ability of fibroblasts to secrete various pro-tumor chemokines, including CXCL12/CXCR4 axis, CCL2, CCL5, CCL7, CXCL8, and CXCL14." (PMID 39092186, 2024). "In contrast, the combination of C‐C motif chemokine ligand 2 (CCL2) and interferon gamma (IFN‐g) can drive an anti‐tumour phenotype in PDAC myeloid cells, and this is particularly important in the presence of CD40 agonist treatment." (PMID 38426634, 2024). "A CCR2 antagonist is a small molecule which targets the CCL2/CCR2 signaling pathway to prevent the recruitment of CCR2-expressing monocytes and macrophages to the tumor site." (PMID 39307417, 2024). "The binding of CCL2 to the CCR2 receptor initiates various signaling pathways that stimulate cell migration and mediate tumor pathogenesis." (PMID 38769475, 2024). "CCL2, also known as MCP-1, is a chemokine produced by a variety of cells including tumor cells, monocytes, macrophages, endothelial cells and other inflammatory cells." (PMID 39334887, 2024). "The underlying mechanisms for the modified MSC-exerted anticancer effects were described as an upregulated expression of monocyte chemoattractant protein-1 (MCP-1/CCL2) and enhanced stimulation of NK cells and cytotoxic T lymphocytes (CTL) in tumour tissues." (PMID 39416732, 2024). "Circulating M-MDSCs infiltrate tumors via the CCL2/CCR2 axis and differentiate into M2-type TAMs44; this cell population plays a pivotal role in assisting tumor growth by suppressing T cell functions and promoting angiogenesis." (PMID 38402307, 2024).
tumor (continued). "It has been reported that M2 type TAMs participate in tumor angiogenesis by secreting pro-angiogenic factors, including VEGF-A, TGF-β, and C-C motif chemokine ligand 2 (CCL2)." (PMID 38842752, 2024). "Also, we explored whether IFI35 or CCL2 affect PD-L1 expression in tumor cells." (PMID 38216673, 2024). "To further evaluate CCL2 expression within TLS regions and surrounding tumor tissue, we performed IHC on TLS+ CRC tissues." (PMID 39595209, 2024). "CCL2 then activates MAPK signaling in tumor cells and increases tumor cell migration and MMP-9 expression." (PMID 39555068, 2024). "The CCL2/CCR2 axis is crucial for monocyte mobilization into the TME, and a myriad of preclinical mouse tumor models have proven this axis is both protumoral and targetable." (PMID 38786066, 2024). "The CCL2/CCR2 axis mediates TAM infiltration, while the application of a natural CCR2 antagonist decreased the number of TAMs in the tumor stroma and shifted them towards the M1-like phenotype, further elevating the number of CD8+ T cells." (PMID 38787372, 2024). "In the bone marrow microenvironment, overexpression of the C–C chemokine ligand 2 (CCL2) secreted by BMA, is the main contributor to tumor growth and metastasis in the obese state." (PMID 38221626, 2024). "The tumor cell analysis of mice injected with miR-126 OE CRC cells and treated with MMPi revealed the lowest HB-EGF, miR-221, CCL2, and the highest miR-126 expression." (PMID 39419989, 2024). "Multiple studies suggest that various cytokines, including chemokines such as CCL2 and LTB4, are key factors that drive MDSC infiltration into the tumour microenvironment and promote their immunosuppressive functions." (PMID 37905494, 2024). "It is recruited to the tumor focus by chemokines such as CCL2 and CCL5 to exert the tumor immunosuppressive function and jointly form the immunosuppressive tumor myeloid microenvironment." (PMID 38279145, 2024). "This polarization diminishes phagocytosis and fosters tumor growth via the CCL2/CCR2 axis, with the suppression of these exosomes proving more efficacious in hindering tumor progression than radiotherapy alone in a zebrafish model." (PMID 38534769, 2024). "CCL2 and CXCL12 (also known as SDF-1) are among the most studied and most widely recognized cytokines recruiting monocytes into tumor tissue." (PMID 38455762, 2024). "The regulation of chemokines has been discussed in several studies, such as the CCL2/CCR2 axis, which promotes the trafficking of monocytes/macrophages into tumor tissues." (PMID 39582864, 2024). "TAMs are drawn to the cancer site by chemokines like C-C motif chemokine ligand 2 (CCL2), and aid tumor development and invasion by secreting cytokines and growth factors including interleukin-6 (IL-6), TGF-β, and VEGF." (PMID 38523646, 2024). "In breast cancer, blockade of the CCL2/CCR2 axis reduces macrophage infiltration and decreases tumor growth." (PMID 39199574, 2024). "Several studies have also shown that the recruitment of CCR1+ myeloid cells via CCR1 ligands, such as CCL2, CCL9 and CCL15, promotes invasion, metastasis, and angiogenesis in CRC and other tumor types." (PMID 38750114, 2024). "S100A4 can stimulate tumor cells to secrete numerous inflammatory cytokines, most notably IL-8 and CCL2, which then shape the TME toward a pro-tumor state and favor metastatic growth." (PMID 38611008, 2024). "TAMs secrete chemotactic factors, such as CCL2 and CCL1, which promote further macrophage recruitment and polarization, as well as migration of other cells, such as tumor-promoting neutrophils, to support an immunosuppressive TME." (PMID 38533720, 2024). "Monocytes are recruited in to the tumor site and differentiate into macrophages upon tissue infiltration, and this process is mediated by inflammatory signals such as CCL2, CCL5, and CSF-1 secreted by tumor cells and other cells within the malignant TME." (PMID 38730724, 2024).
tumor (continued). "Unlike other stromal cells like fibroblasts and macrophages derived from CCL2 in the TME, TANs-derived CCL2 are found in high amounts which facilitates macrophage recruitment and infiltration of the tumor sites." (PMID 38360737, 2024). "For example, CCL2 increases the expression of MMP-9, a protein that degrades the extracellular matrix and removes physical barriers to tumor metastasis." (PMID 39201480, 2024). "In tumor cells with low SLAMF7 expression, using a CCR2 antagonist to inhibit the CCL2/CCR2 axis, generates a greater anti-tumor impact when combined with PD-1 antibody." (PMID 39223632, 2024). "Apart from CCL2, TAN-derived CCL17 (C–C chemokine) recruits CCR4þ and Treg cells for tumor progression." (PMID 38360737, 2024). "Twist1 is also known to transcript CCL2 and CXCL12 that can recruit pro-tumor myeloid cells, serving as a potentially additional mechanism to induce vascular niche-mediated Mφ immunosuppression." (PMID 38416830, 2024). "The recruitment of tumor-associated macrophages (TAMs) to tumor sites is mediated by chemokines such as CCL2, CCL5, CCL7, CXCL1, CXCL2, and CXCL4, which promote tumor survival." (PMID 39769501, 2024). "Compared with conventional anti-MSLN CAR-T cells, CAR-T cells coexpressing CCR2b exhibited increased CCL2-induced calcium flux and transport, increased levels of IL-2, IFN-γ, and TNF-α, and enhanced cytotoxicity against MSLN+ tumor cells in vitro." (PMID 39023820, 2024). "BRAF mutations can lead to the secretion of various cytokines and chemokines (such as CCL2, CCL5, and CXCL8) by tumor cells, altering the surrounding tumor microenvironment." (PMID 39529955, 2024). "N2 favor tumor promotion and TME remodeling through the secretion of MMPs, CCL2/3/4/17, neutrophil elastase, and reactive oxygen species (ROS)." (PMID 39199647, 2024). "Ablation of CCL2/CCR2 axis via neutralizing monoclonal antibodies (mAbs), antisense RNA or genetic manipulation has been shown to inhibit the development of tumor progression and metastasis in bone marrow, breast, liver and lung cancers." (PMID 39003350, 2024). "We validated that EHF promotes the migration and infiltration of TAMs into tumors through the CCL2/CCR2 axis, which complements the function of GLI1 in tumor cells and provides a more comprehensive mechanism for EHF‐mediated cholangiocarcinogenesis." (PMID 38741887, 2024). "Tumor-resident mesenchymal stem cells, known for their significant secretion of a variety of chemokines, including CCL-2, CCL-7 and CCL-12, enhance the recruitment of CCR2-expressing monocytes to tumor sites, thereby increasing the macrophage population." (PMID 38575562, 2024). "Several features were enriched in responders at both BL and C2, including increased abundance of serum CCL2 and GZMA and tumor gzma and gzmh mRNA." (PMID 38670099, 2024). "Recruitment and education of Gr1+CD11b+ cells in the TME, particularly through the chemokines CCL2, CXCL1, and CXCL2 or IL-33, are considered critical steps for their contribution to tumor progression and metastasis." (PMID 38236642, 2024). "Results have shown that chemokines produced by tumor cells promote the infiltration of immune cells into the tumor microenvironment (TME), and that MCP-1 (CCL2) plays a decisive role in this context." (PMID 39882242, 2024). "RANKL produced by these cells can stimulate a tumor’s secretion of PTHrP, which in turn indirectly induces osteoclast formation by upregulating osteoblast production of RANKL and C-C motif chemokine ligand 2 (CCL2)." (PMID 39595017, 2024). "TAMs are usually dependent on chemokines such as CCL2, CCL5 and CXCL12 for recruitment from peripheral monocytes/macrophages into the TME at the primary tumor site." (PMID 39135069, 2024). "TIDC can produce chemokines (CCL2 and CCL3), cytokines (TNF-α and IL-6) and growth factors (VEGF and CCL5), which promote tumor angiogenesis and cancer cell proliferation as well as metastasis." (PMID 39470950, 2024).
tumor (continued). "Our computational analysis suggests that HPV − tumor cells have a stronger reliance on IL6/IL6R and CCL2/CCR2 signaling within the tumor microenvironment (TME) to evade NK cell immune attack, in contrast to HPV + tumors." (PMID 38468260, 2024). "The cytokines that exhibited a particularly strong positive correlation with tumor burden were CXCL10 (IP-10) (r = 0.8492, p = 0.0009) and CCL2 (r = 0.7851, p = 0.0042), also known as MCP-1." (PMID 39623404, 2024). "Monocyte chemoattractant protein-1 (MCP-1/CCL2) was isolated in 1989 and found to be structurally identical to tumor cell-derived chemotactic factor (TDCF), responsible for tumor-associated macrophage (TAM) infiltration." (PMID 39206193, 2024). "They indicated that this increase in the level of serum CCL2 positively correlated with the progression of NPC, indicating that NPC tumours secrete CCL2 to recruit monocytes from the bone marrow." (PMID 38888489, 2024). "After THC treatment, a decrease was observed in the level of six cytokines in serum samples, including IL-6 and TNF-α, as well as chemokine (C-C motif) ligand 2 (CCL2), known for its unfavorable effects on tumor prognosis, and reviewed elsewhere." (PMID 38799159, 2024). "Mechanistically, CD248 + mechanoresponsive CAFs approached and lined the tumor nest to physically block the infiltration of CD8 + T cells and drug delivery, while IL6 + CCL2 + immunomodulatory CAFs induced therapeutic resistance with distinct IL-6 expression." (PMID 39334513, 2024). "In an NSCLC mouse model, the administration of anti-murine-CCL2/CCL12 monoclonal antibodies resulted in reduced tumor growth and increased the influx of CD8+ T cells into the tumor." (PMID 38928238, 2024). "Moreover, inhibiting both AR and CCL2/CCR2 signaling could reduce tumor progression in vivo." (PMID 39286635, 2024). "Activation of the PI3K pathway in response to immunotherapy promotes the increased expression of CCL2 (chemokine ligand 2) and VEGF immunosuppressive cytokines and reduction in CD8+ T cell tumor penetration." (PMID 38398094, 2024). "At last, we confirmed that cisplatin induces oxPAPC release, and thus promotes MDSCs infiltration to tumour via activating the MCP‐1/CCL2 and LTB4/LTB4R axis, potentially boosting tumour growth." (PMID 37905494, 2024). "In the present study, by integrating scRNA-seq data with TCGA HNSCC dataset, we identified five enriched pathways, including IL6/IL6R and CCL2/CCR2 signaling, within NK cells and tumor cells in the HPV − HNSCC cohort compared to the HPV + counterpart." (PMID 38468260, 2024). "Cancer cells release CCL2 into the circulation, which recruits tissue macrophages and CCR2-expressing Ly6Chi monocytes to the tumor site, where they differentiate into TAMs, thereby increasing the number of TAMs within the TME." (PMID 39350256, 2024). "In contrast, N2 neutrophils support tumor expansion by expressing arginase, matrix metalloproteinase-9 (MMP-9), VEGF, and chemokines such as CCL2, CCL5, and CXCL4." (PMID 39795864, 2024). "Expression analysis by qPCR, using human-specific primers, showed a significant increase in the expression of some chemoattractant factors (i.e., CCL2 and CSF1) of the cell-cycle inhibitor P21 in the tumor cells of PTP4A2-KO xenografts." (PMID 38904264, 2024). "Our study illuminates the role of CEBPB in GBM subcluster 6, demonstrating its ability to recruit and polarize macrophages into the M2 phenotype by regulating the secretion of CCL2 and SPP1 by tumor cells." (PMID 38994023, 2024). "For example, Wnt5a is able to secrete the chemokine CCL2 through the Wnt5a-CaMKII-ERK pathway, altering the tumor microenvironment and promoting tumor cell proliferation and migration." (PMID 39598398, 2024). "SUSD2 can directly regulate the expression of chemokine (C-C motif) ligand 2 (CCL2), which is responsible for recruiting macrophages to the tumor microenvironment." (PMID 39791720, 2024).
tumor (continued). "The data showed specific deletion of β3 integrin in pericytes does not affect tumor angiogenesis but instead fuels tumor growth by secreting CCL2, thereby directly activating the MEK1-ERK1/2-ROCK2 signaling pathway in tumor cells." (PMID 38528180, 2024). "Increases expression of CCL2 and VEGF immunosuppressive cytokines; reduces CD8+ T cell tumor penetration; increased extrinsic PD-L1 expression." (PMID 38398094, 2024). "It is believed that monocyte-attracting chemokines are primarily responsible for macrophage infiltration in tumors, such as CCL2 and CCL5 that can be produced by tumor cells, endothelial cells, macrophages, and fibroblasts within the tumor microenvironment." (PMID 39628476, 2024). "The secretion of CCL2 by UBC cells and IL-6 by macrophages within the TME acted in concert to augment tumor stemness and promote UBC progression." (PMID 39479456, 2024). "Cytokines and chemokines in TME, such as CSF1, GM-CSF, IL-1β, CCL2, and VEGF, can induce conformational changes in α4β1 integrins to promote myelopoiesis, monocyte-to-tumor trafficking, and infiltration by activating the corresponding signaling pathways." (PMID 38185636, 2024). "Earlier findings in mice identified the key role of CCL2 in recruiting CCR2+ monocytes to metastatic sites, where they promote the extravasation of tumour cells and facilitate tumour metastasis." (PMID 38903497, 2024). "E3 ligase UBR5 promotes the release of paracrine factors like CCL2 and CSF-1, leading to increased TAM infiltration and promoting tumor cell proliferation." (PMID 39223632, 2024). "Since tumor and stromal cells bear CCL2 ligands, these monocytes are recruited due to the high number of expressed CCR2 receptors for CCL2 chemokine." (PMID 39766202, 2024). "Among them, Macro-2 seems to be a key player in the tumor metastatic cascade, characterized by expression of SPP1, CCL18, CXCL5, CCL2, and CCL7." (PMID 38281962, 2024). "Six out of 18 chemokines/cytokines assessed were significantly decreased in the ascites from NLRC5+ tumor-bearing mice, including IL-6, IL-10, IL-12, CXCL10, CCL5, and to a greater extent, CCL2." (PMID 38235131, 2023). "CCL2 and CCL3 influence monocyte recruitment and production of MMP9, thus promoting tumor invasion and metastasis." (PMID 37947617, 2023). "PTX3, CCL2, and CXCL12 are stroma-derived factors that increase the proliferation rate of mutant desmoid tumor cells." (PMID 37377751, 2023). "Such chemokine signaling involved the receptors for CCL2 (CCR2), CCL5 (CCR5), and CXCL12 (CXCR4), which also enhanced STAT-3 activity and M2 polarization of macrophages and retention inside the tumor." (PMID 36902456, 2023). "For instance, HFD-induced obese mice showed increases in VEGF, IL-6, chemokine ligand 2 (CCL2), and C-X-C motif chemokine ligand 1/2/13 (CXCL1/2/13), which promote angiogenesis and the infiltration of immune cells that favor tumor development and metastasis." (PMID 36670988, 2023). "IFN-β, IL-6, CXCL10, CCL2, and CCL5 have been reported to be induced in tumor cells by ATRi plus RT in vivo and/or in vitro." (PMID 36810257, 2023). "To validate the carcinogenic effect of CCL2, we employed pirfenidone (PFD), a CCL2 inhibitor, to treat MB49 cell‐C57BL/6 J mouse bladder orthotopic tumor models." (PMID 37743226, 2023). "recently confirmed that microglial genes (CX3CR1, TMEM119, and P2RY12) were mainly expressed in the periphery, while activated macrophage genes (TNF, CCL2, LYZ, CCR2, CXCR4, and SIGLEC1) were predominantly detected within the core tumor regions." (PMID 37731483, 2023). "Due to the role of various chemokines (such as CCL2 and CCL5) and cytokines (for example, CSF1 and members of the VEGF family) at the tumor site, monocytes are recruited at the tumor site to form TAMs." (PMID 37111726, 2023). "Macrophages express CCR2 were recruited by CCL2 that result in up regulating their expression levels of angiogenic factors, such as IL− 6, VEGF, and MMP9, which contributed to tumor vascularization." (PMID 36816959, 2023).